MYCN (MYCN proto-oncogene, bHLH transcription factor)
Diseases named in the same sentence as MYCN in open-access papers (continued):
Sharing a sentence is not in itself a finding about the gene and the disease.
tumor (continued). "The amplification of MYCN was assessed by the number of fluorescent hybridization signals within the nuclei of tumor cells." (PMID 23445749, 2013). "The phosphoproteome of the MYCN-amplified tumor cells was characterized by high levels of phosphopeptides, including numerous mediators of intracellular signaling cascades." (PMID 24349301, 2013). "In contrast, type 2B tumours are signified by amplification of MYCN, often in conjunction with 1p deletion and 17q gain in a near-diploid or near-tetraploid background." (PMID 23555645, 2013). "These tumor suppressive effects of miR-34a are mediated by changes in a number of target mRNAs including MYCN, CDK4, cyclin D1, SIRT1 and Bcl-2." (PMID 22629428, 2012). "We note that one previous report did not detect a difference in clinical MIBG avidity according to tumor MYCN status." (PMID 23050139, 2012). "Patients having either a MYC or MYCN amplification in their tumor clearly have a significantly worse outcome compared to cases without amplification." (PMID 22358457, 2012). "S69K was then used to generate CTL from peripheral blood mononuclear cells of an HLA-A1+ normal donor and an HLA-A1+ NB patient carrying a MYCN-amplified tumor." (PMID 23162796, 2012). "Reactivity of patient or normal CTL to MYCN peptide was not investigated in this study, but it is conceivable that MYCN peptide-specific CTL can be generated using tumor mRNA DC transfection from NB patients carrying MYCN-amplified tumors." (PMID 23162796, 2012). "Tumor formation is dependent on the level of MYCN gene dosage, with homozygous mice developing tumors with a short latency and 100% tumor penetrance, and hemizygous mice displaying longer tumor latency and only 20–30% penetrance." (PMID 23181218, 2012). "Recognition of tumor cells by these CTL was found to depend on MYCN amplification and HLA specificity, since CTL lysed only MYCN-amplified primary NB cells that expressed HLA-A1." (PMID 23162796, 2012). "This innovative model has allowed to broaden knowledge on NB pathogenesis and design therapeutic strategies aimed at inhibiting expression of MYCN protein and consequently dampening tumor growth." (PMID 23162796, 2012). "MYCN-DNA vaccination was performed before challenge with tumor cells and resulted in reduction of primary tumor growth as well as in antigen-specific target cell killing." (PMID 23162796, 2012). "Intriguingly, CX3CL1 down-modulation was observed in MYCN-amplified primary NB tumors, supporting a role in limiting tumor aggressiveness." (PMID 22253825, 2012). "The in vivo model utilizes two cell lines which were modified to stably express luciferase, NB1691 (MYCN amplified) and SK-N-AS (derived from a non-MYCN amplified tumor with LOH for chromosome 11 q)." (PMID 22662276, 2012). "To detect tumor-derived endothelial cells (TECs) in NB microenvironment we have used a combination of fluorescent in situ hybridization (FISH) for MYCN and immunofluorescence for endothelial cell marker, mainly CD31." (PMID 23162796, 2012). "In NB, the most described epigenetic alterations are DNA methylation of CASP8 and RASSF1A, both associated with risk factors, such as MYCN amplification (MNA), age at diagnosis and tumor stage." (PMID 23034519, 2012). "Regarding genetic alterations diagnosed by FISH on TMAs, 5.6% were MYCN gain tumours, 13.3% presented 1p36 deletion, 14.2% harboured 11q deletion and 34.9% showed 17q gain." (PMID 21654680, 2011). "The over-expression of MYCN and Let-7 targets in C5 tumours adds weight to the functional significance of the amplification and over-expression of MYCN and the significant reduction in expression of Let-7 alleles." (PMID 21533284, 2011).
tumor (continued). "All the 17 samples assigned to the hierarchical cluster 3 (h3) were stage 4, MYCN amplified tumours with high frequency of del1p." (PMID 21492432, 2011). "MYCN amplification (MNA) in the tumour is closely related to poor survival of the patients, despite all modern multi-modal treatment efforts." (PMID 21654684, 2011). "By contrast, MYCN was significantly over expressed in C5 tumours (AOCS p<0.0001, TCGA p<0.0001, two sided Mann Whitney test)." (PMID 21533284, 2011). "Two cell lines, both containing a stable, constitutively expressed luciferase reporter construct for measuring tumor growth were used, NB1691luc (MYCN amplified) and SK-N-ASluc (non MYCN amplified)." (PMID 21266077, 2011). "We observed highly specific deregulation of individual members of the MYCN-Lin28B-Let7 pathway in C5 tumours, as well as a broader set of MYCN and Let7 transcriptional targets." (PMID 21533284, 2011). "The prognosis of NB patients depend upon clinical factors as stage, age at diagnosis, tumour histopathology, and several genetic factors as MYCN amplification (MNA) status and DNA index." (PMID 21492432, 2011). "Regarding the non-MYCN-amplified tumours, it is noteworthy that the average expression values for the three miRNA from stage 4 patients <18 months (n=11) were higher than those ⩾18 months (n=49)." (PMID 21970883, 2011). "Next, the data were stratified according to age, stage and MYCN amplification on the whole cohort of 227 tumours (13 of the preliminary cohort and 214 of the validation set)." (PMID 21970883, 2011). "The tumour-suppressor miRNA mir-34a has been experimentally validated to directly target the 3′UTR sequence of MYCN." (PMID 21654684, 2011). "Apart from the intrinsic difficulty of targeting a transcription factor, the development of MYCN-targeting drugs is hampered by its extremely high expression in tumour cells." (PMID 21304178, 2010). "Given their reliance on B-MYB, tumours with amplification of MYCN should be exquisitely sensitive to its pharmacological targeting, indicating that the search for small molecule inhibitors of B-MYB is warranted." (PMID 21304178, 2010). "The INRG Biology Committee agreed that MYCN status should be evaluated in every resected neuroblastic tumour, including the Schwann cell stroma-rich categories." (PMID 19401703, 2009). "Stage 4 tumours were 90% near-diploid/tetraploid, 44% MYCN amplified, 77% had 1p LOH (50% 1p36), 23% 11q and/or 14q LOH (27%) and 47% had 17q gain." (PMID 19192278, 2009). "Chromosome 14q LOH of at least one locus was identified in 6/22 stage 4 tumours, a majority MYCN NA, while chromosome arm 14q was preserved in all 9 stage 4s tumours." (PMID 19192278, 2009). "Tumour markers such as MYCN amplification, histology, ploidy, and NTRK1 expression have proven prognostic value in large cohorts of NB patients." (PMID 19192278, 2009). "The MYCN oncogene is generally single-copy in stage 4s tumours but recent studies of infant NB have identified some cases of MYCN-amplified tumours otherwise compatible with clinical stage 4s." (PMID 19192278, 2009). "These tumours frequently show segmental aberrations and high-level amplification of the MYCN locus is detected in a substantial subset." (PMID 19401703, 2009). "To more exactly determine MYCN copy number in the tumours that were studied, we performed a genomic quantitative PCR (gQPCR) using genomic primers recognizing five different locations within the MYCN-gene." (PMID 19615087, 2009). "Amplification of MYCN is associated with advanced stages of disease and the 3-year event-free survival of tumours with MYCN amplification is <20%." (PMID 18769732, 2008). "Because DMs lack centromeric sequences it has been unclear how NB cells retain and amplify extrachromosomal MYCN copies during tumour development." (PMID 18769732, 2008). "To date, few studies have focused on the prognostic impact of these various genetic markers in a multivariate setting, especially in MYCN non amplified tumours." (PMID 17579628, 2007).
tumor (continued). "In the intrinsic route, increased levels of the antiapoptotic protein Bcl-2 in primary NBs correlate with unfavourable histology according to Shimada and with MYCN amplification, and seem to promote tumour cell survival." (PMID 16755292, 2006). "In NB, resistance to TRAIL-induced apoptosis has been preferentially described in MYCN-amplified tumours and correlates with inactivation of caspase 8 gene secondary to gene deletion or silencing through DNA hypermethylation." (PMID 16755292, 2006). "The primary tumour was judged MYCN amplification by the FISH method that was performed after the relapse." (PMID 16670717, 2006). "A significantly higher proliferative activity was only detected in the small subgroup of MYCN amplified tumours." (PMID 16755292, 2006). "The most common genetic features of this tumour are amplification of the oncogene MYCN, deletions of part of chromosome arm 1p, gain of parts of 17q and triploidy." (PMID 16359544, 2005). "This is in agreement with the murine MYCN transgenic model of NB where the MYCN transgene itself is enough for tumor development, but these tumors develop additional genomic changes characteristic of NB." (PMID 15380028, 2004). "In this study, the aim was to develop NPs that reduce the activity of mTOR and AURORA pathways, potentially decreasing MYCN protein enhancement and stability, by combining inhibitors and targeting them specifically to the tumor, and to demonstrate their effect in NB." (PMID 41926246, 2026). "We also noted target engagement in the tumor tissues, with decreased expression of MYCN, pBRD4, and H3K27ac, strengthening the hypothesis that these are the mechanisms involved." (PMID 41539997, 2026). "Additionally, we observed strong synergism between DPI and MitoQ in reducing cell viability of MNA cells and a 3D MYCN-driven NB tumor model." (PMID 41211440, 2025). "However, their presence waned in SMG samples from 6-week-old Th-MYCN+/− mice and tumor tissue from 3-week-old Th-MYCN+/+ mice." (PMID 40580553, 2025). "Notably, MYCN amplification emerged as a significant predictor of survival outcomes and a key driver of differential gene expression in the tumor samples." (PMID 39860532, 2025). "Consequently, targeting MYCN cofactors represents one strategy to block MYCN’s tumor-promoting function." (PMID 40274766, 2025). "By reinstating the S-nitrosylation of MYCN, NO-based therapies could re-regulate key signaling pathways that promote ER stress, inhibit transdifferentiation, and reduce the overall tumor burden in NEPC." (PMID 41198652, 2025). "However, in hemizygous Th-MYCN mice, a single allele knockout was sufficient to prolong survival, suggesting a gene dosage effect between MYCN and PA2G4 in driving tumor progression." (PMID 41002386, 2025). "Our previous study demonstrated that MYCN overexpression is associated with liver tumorigenesis and HCC progression through lipid desaturation-mediated membrane reprogramming and miRNA-based signaling regulation, such as by the tumor-suppressor miR-493-5p." (PMID 40027135, 2025). "We hypothesize that this tumor arises from a primitive photoreceptive progenitor cell common to both the pineal gland and retina hence carrying both features with MYCN amplification driving its aggressive behavior." (PMID 41353556, 2025). "It has been suggested that ID2 might acts as a MYCN effector, promoting tumor initiation and maintenance." (PMID 40365336, 2025). "However, ONC201 only inhibited tumor development in xenograft tumors derived from NB cells with amplified MYCN; this inhibition correlated with a substantial reduction in MYCN protein levels and the reactivation of ATRX expression." (PMID 40210723, 2025). "Involvement of PCSK1N in metabolic and immune‐related pathways may indicate its role in modulating tumor microenvironment, potentially aiding tumor progression and immune evasion in MYCN‐amplified." (PMID 40600620, 2025).
tumor (continued). "Similar to MYCN-amplified tumours, the common and likely initiating events in the founder clone (C0) were large-scale chromosome 10 loss and/or chromosome 17q gain, with subclonal MYC amplification occurring later during tumour evolution." (PMID 40335697, 2025). "CNAs in ABL2, MDM3, and MYCN genes were identified in 18 tumor samples." (PMID 40332023, 2025). "Indeed, reducing cysteine uptake triggers ferroptosis, resulting in tumor remission in an orthotopic MYCN-amplified NB model." (PMID 40507292, 2025). "Pharmacological inhibition of KLHL37 arrests the tumor growth of MYCN-amplified xenografts in vivo." (PMID 40493396, 2025). "We further hypothesized that NO-induced S-nitrosylation could interfere with the binding of various protein partners to MYCN, thus impairing its ability to promote tumor progression in NEPC cells." (PMID 41198652, 2025). "However, further research is necessary to develop more effective therapies and improve survival outcomes for patients with MYCN-driven tumor." (PMID 40365336, 2025). "Similarly, miR-19b-3p has been reported to function as a tumor-suppressive miRNA in EC by regulating MYCN." (PMID 41226475, 2025). "This raised questions about whether 80% of Th-MYCN+/− mice experienced tumor initiation or if 20% potentially underwent spontaneous regression." (PMID 40580553, 2025). "In the present study, ONC201 treatment did not suppress either c-Myc or LGR5 expression, which may have led to the failed decrease in tumor vessel formation within non-MYCN-amplified NB xenografts." (PMID 40210723, 2025). "Except for the interfering small RNA, the MYCN-targeting pyrrole-imidazole polyamide (PIP) MYCN-A3 can directly bind to and alkylate MYCN transcripts, downregulating MYCN expression and inhibiting tumor progression in the MNA-NB mouse xenograft suppressor model." (PMID 41244073, 2025). "These structural genetic alterations are associated with aggressive tumor behavior, poor prognosis, and a higher likelihood of relapse independent of the poor prognosis associated with MYCN amplification." (PMID 40104501, 2025). "Tumor MYCN amplification was present in 36 (43.4%) patients." (PMID 41294259, 2025). "Particularly when MYCN expression stays unabated, this addiction makes treatment plans more difficult since tumor cells might avoid regular drugs by means of several resistance mechanisms." (PMID 40429864, 2025). "Moreover, in another study, it was found that the inhibition of fatty acid transport protein 2 (FATP2) resulted in the suppression of MYCN-induced glycerolipid accumulation and tumor growth in preclinical NB models." (PMID 40507292, 2025). "A well‐known regulator of the cell cycle and proliferation, the enrichment of E2F4 suggests that the key genes may be connected to cell cycle control, consistent with aggressive tumor behavior or high MYCN activity." (PMID 40600620, 2025). "Similarly, suppression of MYCN in NB models leads to the upregulation of the glucocorticoid receptor (GR), which inhibits tumour progression and promotes differentiation." (PMID 40779030, 2025). "Another possibility is that the acquisition of malignant characteristics requires additional genetic/epigenetic changes to fully promote tumor growth, which could be induced by MYCN dosage." (PMID 40580553, 2025). "Higher EPOR expression is associated with unfavourable prognosis both for MYCN non-amplified NB tumours and in relapsed tumours." (PMID 41511287, 2025). "This may explain how MYCN functions as a key regulator during early development and implies that the oncogenic functions of MYCN during tumor development may be due to its maintenance of cancer stem cells." (PMID 39802403, 2025).
tumor (continued). "The glycolytic genes, HK2, GAPDH and ENO1, were chosen as they mediate early, mid and final stages of glycolysis respectively, and all three ketolytic genes BDH1, OXCT1 and ACAT1 were analysed for MYCN amplification, survivability and tumour stage progression in three NB datasets." (PMID 41420301, 2025). "Recent studies by the Eilers group added further nuance: MYC protein has been observed to multimerize at stalled replication forks, and MYCN can recruit the nuclear exosome targeting complex to nascent RNAs leading to S phase progression and tumour cell stress resilience." (PMID 41561634, 2025). "By comprehensively assessing the expression of 19 genes in NB tumor samples and cell lines, it was discovered that the mRNA expression level of AKR1C1 was significantly elevated in both high-risk NB groups and SK-N-BE2 (MYCN amplification NB cell line)." (PMID 39964621, 2025). "All mice homozygous for the MYCN transgene develop tumours by 7 weeks of age54,55." (PMID 40766251, 2025). "Additionally, the involvement of resting CD4 memory T cells suggests a potential dysregulation of adaptive immunity in MYCN‐amplified NB, indicating a mechanism by which the tumor evades immune surveillance." (PMID 40600620, 2025). "In addition, our data challenge the cutoffs used for a tumour to be called MYC/MYCN-amplified by FISH, as even the smallest MYC subclones, which initially have low abundance, have the potential to expand into the dominant clone during relapse." (PMID 40335697, 2025). "Importantly, in this study, amplification in MYCN observed in the tumor DNA samples was also detected in the cfDNA." (PMID 40386554, 2025). "Our results are in agreement with those reported in the literature and add new insights into how the MYCN-amplified clone’s reproductive advantage in a tumour, its gene expression profile, the tumour’s other clones (with different mutations), and the tumour’s microenvironment are inter-related." (PMID 39715281, 2024). "MYCN amplification and ALK mutations promote tumor angiogenesis and vasculogenesis through the secretion of vascular endothelial cell growth factor (VEGF) by cancer cells and other cells residing in the TME, such as mesenchymal stromal cells (MSCs) and endothelial cells." (PMID 38542199, 2024). "This would suggest that prolonged actions of MYCN in the tumour cells may facilitate dedifferentiation of the original cPR phenotype." (PMID 37606819, 2024). "The study supporting this claim compared tumours without this mutation, tumours wherein MYCN was homogeneously amplified (more than 20% of cancer cells exhibited MYCN amplification), and tumours wherein it was heterogeneously amplified." (PMID 39715281, 2024). "Furthermore, CDK7 and BET‐Bromodomain inhibitors have exhibited anti‐tumor efficacy by targeting MYCN in various cancers." (PMID 39248163, 2024). "In addition, the heterogeneity of MYCN amplification in a tumour is known to influence its clinical features." (PMID 39715281, 2024). "The assessment of MYCN amplification on intraoperative tumor imprints does not cause any diagnostic problems." (PMID 39049899, 2024). "Further, five children had significantly higher tumor-related parameters in laboratory tests with MYCN gene and chromosomal abnormalities and had developed systemic multiple metastases, and previous case reports also mentioned that MYCN amplification and systemic multiple metastases were found." (PMID 38403682, 2024). "To date, the tumor take and growth seem to be independent from tumor stage and MYCN status." (PMID 38351008, 2024). "In theory, this could reflect an inability of high MYCN–expressing HGSC tumor cells to give rise to stable cell lines." (PMID 38748789, 2024). "With respect to heterogeneously MYCN-amplified tumours only, the genomic background (chromosomal aberrations) of such a tumour, the reproductive advantage of the MYCN-amplified clone therein, and its disease outcome are known to be related in a counter-intuitive manner." (PMID 39715281, 2024).